ELK3 (ETS transcription factor ELK3)
Diseases named in the same sentence as ELK3 in open-access papers (continued):
Sharing a sentence is not in itself a finding about the gene and the disease.
gastric cancer (4 papers, 2021 to 2025). A primary or metastatic malignant neoplasm involving the stomach. "The analysis of various gastric cancer cell lines and gastric cancer patient samples also revealed a positive association between ELK3 and BMP1, LOXL2, SNAI1, SERPINF1, DCN, and NID1, and these genes were associated with a poor prognosis." (PMID 35409069, 2022). "Our in silico analyses indicated that ELK3 expression was positively associated with these ECM remodeling-related genes in gastric cancer cells and patient samples." (PMID 35409069, 2022). "Our study identified a molecular network of ELK3-mediated gastric cancer cell migration and invasion, the underlying mechanism of which is the regulation of ECM remodeling." (PMID 35409069, 2022). "Here, we investigated whether ELK3 expression is functionally associated with the metastatic phenotype of gastric cancer." (PMID 35409069, 2022). "ELK3 is highly expressed in patients with gastric cancer; however, the association between ELK3 expression and gastric cancer progression remains unknown." (PMID 35409069, 2022). "However, the functional link between the ELK3 gene and ECM on gastric cancer cell migration is not yet fully understood, although the high expression of ELK3 in patients with gastric cancer is closely associated with cancer progression." (PMID 35409069, 2022). "For example, ELK3 increases cell migration and the invasion of gastric cancer through the regulation of extracellular matrix remodeling-associated genes." (PMID 38632244, 2024). "The present study demonstrated that ELK3 regulated the expression of certain ECM remodeling-related genes to induce gastric cancer cell migration and invasion." (PMID 35409069, 2022). "To examine the effect of ETS transcription factor ELK3 (ELK3) on the cell dissemination capacity of gastric cancer cells, we examined ELK3 mRNA expression in various gastric cancer cell lines using the Cancer Dependency Map (DepMap) database." (PMID 35409069, 2022). "In conclusion, our finding suggests that ELK3 contributes to gastric cancer cell dissemination by regulating the expression of ECM remodeling-related genes." (PMID 35409069, 2022). "The gene analysis of samples from patients with gastric cancer indicated that a high ELK3 expression is positively correlated with BMP1, LOXL2, SNAI1, SERPINF1, DCN, and NID1 expression, all of which are closely associated with a poor prognosis." (PMID 35409069, 2022). "Collectively, these findings suggest that ELK3 acts as an important regulator of gastric cancer cell dissemination by regulating ECM remodeling." (PMID 35409069, 2022). "Here, we demonstrate that the E26 transformation-specific (ETS) transcription factor ELK3 (ELK3) gene is required for the migration and invasion of gastric cancer cells." (PMID 35409069, 2022). "The high expressions of ELK3 and other ECM remodeling-related genes were also closely associated with a worse prognosis of patients with gastric cancer." (PMID 35409069, 2022). "The overall survival of patients with gastric cancer with a high expression of ELK3 was significantly lower than that of patients with a low expression." (PMID 35409069, 2022). "More importantly, we have identified ELK3 as a new biomarker for gastric cancer, which is beneficial to the precise treatment of gastric cancer." (PMID 34233659, 2021). "Our in vitro studies have shown that inhibiting the expression of ELK3 in gastric cancer cell lines reduces its proliferation ability and increases its apoptosis level." (PMID 34233659, 2021). "Among them, ELK3 was proved in vitro, and downregulation of its expression inhibited the proliferation of gastric cancer cells, induced proliferation, and exerted anti-tumor effects." (PMID 34233659, 2021). "5-Ethynyl-2′-deoxyuridine and Acridine Orange/Ethidium Bromide staining, flow cytometry and Western-Blot detection were used to analyze the effects of hub-TF ELK3 on the proliferation and apoptosis of gastric cancer in vitro." (PMID 34233659, 2021).
gastric cancer (continued). "In order to verify the effect of ELK3 on the proliferation of gastric cancer, we performed EDU staining." (PMID 34233659, 2021). "We also analyzed ELK3 mRNA level and protein level with five gastric cancer cell lines." (PMID 35409069, 2022). "We found that ELK3 regulated the migration and invasion of gastric cancer cells." (PMID 35409069, 2022). "Our findings demonstrated that ELK3 promoted gastric cancer cell migration and invasion." (PMID 35409069, 2022). "However, E-cadherin and Fibronectin expression were no different between control and ELK3-depleted SNU638 cells, suggesting ELK3-mediated cell migration and invasion in gastric cancer cells is unnecessary for E-cadherin." (PMID 35409069, 2022). "In addition, using The Human Protein Atlas (HPA) to analyze the protein expression of hub TFs, ELK3 immunohistochemical staining intensity in normal tissues is lower than gastric cancer tissues, while ZNF300 and MEF2B are higher than gastric cancer tissues." (PMID 34233659, 2021). "The expression of ELK3 in gastric cancer is positively correlated with poor prognosis." (PMID 34233659, 2021). "Notably, the analysis of patients with gastric cancer indicated the marked positive regulation of ELK3 and BMP1, LOXL2, SNAI1, SERPINF1, DCN, and NID1 gene expression, suggesting a significant positive correlation between ELK3 and ECM remodeling-associated genes in gastric cancer." (PMID 35409069, 2022). "Therefore, further analysis of the role played by ELK3 in gastric cancer cells." (PMID 34233659, 2021). "The data from in silico analyses indicate that ELK3 positively regulate the expression of ECM remodeling-related genes, resulting in a poor prognosis of patients with gastric cancer." (PMID 35409069, 2022). "The analysis of data from TCGA and GTEx revealed that ELK3 and BMP1, and LOXL2 were highly expressed in the gastric cancer samples compared with the healthy samples." (PMID 35409069, 2022). "Subsequently, the clinical relevance between the ELK3 gene and ECM remodeling-related genes and the prognosis of patients with gastric cancer were examined using Kaplan-Meier survival plots." (PMID 35409069, 2022). "First, the correlation between ELK3 expression and BMP1, LOXL2, SNAI1, SERPINF1, DCN, and NID1 expression was analyzed in 19 different gastric cancer cell lines." (PMID 35409069, 2022). "Our finding demonstrated that the ELK3-mediated genetic network in ECM remodeling contributed to the migration and invasion of gastric cancer cells." (PMID 35409069, 2022). "The results suggested that the expression of ELK3 and SP6 is increased in gastric cancer, and the expression of ZNF300 and MEF2B is down-regulated in gastric cancer." (PMID 34233659, 2021). "From these analyses and a previous report, we selected gastric cancer cell lines exhibiting a relatively low and high expression of the ELK3 gene (SNU484 and SNU638 cells, respectively) and further examined the molecular link between ELK3 and cell migration." (PMID 35409069, 2022). "In gastric cancer, ELK3 has no experimental studies to confirm its function." (PMID 34233659, 2021). "The ELK3 expression in gastric cancer cells and human gastric cancer samples positively correlated with that of BMP1, LOXL2, SNAI1, SERPINF1, DCN, and NID1, suggesting that this gene signature may be predictive molecular markers for aggressive gastric cancer progression." (PMID 35409069, 2022).
leukemia (4 papers, 2020 to 2025). A malignant (clonal) hematologic disorder, involving hematopoietic stem cells and characterized by the presence of primitive or atypical myeloid or lymphoid cells in the bone marrow and the blood. "In ETV6-RUNX1+ ALL, scRNA-seq revealed elevated activity of B-lineage differentiation transcription factors (TFs), also including the former leukemia genome-wide association study hit ETS domain-containing protein Elk-3 (ELK3)." (PMID 34830811, 2021). "Further functional studies on the lncRNA, ELK3 spliceforms, and the impact of the GWAS risk variants on expression of ELK3 in normal pro-B cells and leukemia are thus warranted to characterize their role during leukemogenesis." (PMID 33218352, 2020). "Using this comprehensive reference for regulatory factors coordinating B-lineage differentiation, our analysis of ETV6-RUNX1-positive ALL cases revealed elevated activity of multiple ETS-transcription factors in leukemic cells states, including the leukemia genome-wide association study hit ELK3." (PMID 33218352, 2020). "Consistently, down-regulation of Elk3 was also found in primary murine Fto−/− leukemia cells, suggesting that the activation of ELK3 expression by FTO is an evolutionarily conserved regulatory mechanism in human and mouse." (PMID 40435251, 2025). "Among the E/R+ TF network, ELK3 and SP4 have been reported to confer risk of leukemia development in GWAS." (PMID 33218352, 2020).
ovarian carcinoma (4 papers, 2019 to 2023). A malignant neoplasm originating from the surface ovarian epithelium. "Meanwhile, circ_0000144 overexpression promotes ELK3 protein expression through the sponging of miR-610, causing ovarian cancer cell proliferation, migration, and invasion." (PMID 36243865, 2022). "Therefore, we investigated the association between circ_0000144 and ELK3 while detecting the expression of circ_0000144 in ovarian cancer." (PMID 36243865, 2022). "ELK3, the expression of which is considerably elevated in CDDP-resistant ovarian cancers, was identified as one of these superenhancer-associated transcription factors." (PMID 37422450, 2023). "In the present study, we found that ELK3 was co-overexpressed with circ_0000144 in ovarian cancer cells." (PMID 36243865, 2022). "This study further demonstrated that circ_0000144 downregulated ELK3 levels by sponging miR-610 in ovarian cancer cells." (PMID 36243865, 2022). "Taken together, these findings indicate that miR-610 impairs ELK3 expression to block ovarian cancer development in vitro." (PMID 36243865, 2022). "Furthermore, mechanistic investigations indicated that circ_0000144 exhibited a tumor promoter role by sponging miR-610 and increasing ELK3 expression in ovarian cancer cells." (PMID 36243865, 2022). "Moreover, knockdown of ELK3 inhibited proliferation, migration, and invasion of ovarian cancer cells." (PMID 36243865, 2022). "Overexpression of ELK3 also occurs in ovarian cancer cell lines and human tumors." (PMID 36243865, 2022). "Moreover, circ_0000144 knockdown significantly inhibit the expression of ELK3 and suppress ovarian cancer progression." (PMID 36243865, 2022). "We further demonstrated that miR-610 suppressed ELK3 expression and that circ_0000144 could promote ELK3 expression by sponging miR-610 in ovarian cancer cells, which enhanced ovarian cancer cell proliferation, migration, and invasion." (PMID 36243865, 2022). "Therefore, the circ_0000144/miR-610/ELK3 network may promote a new treatment strategy for patients with ovarian cancer." (PMID 36243865, 2022). "Therefore, we speculate that circ_0000144 acts as a sponge for miR-610 to enhance ELK3 expression and inhibit ovarian cancer cells." (PMID 36243865, 2022). "Although previous studies have also demonstrated that ELK3 expression is altered in ovarian cancer cell lines and tumors through overexpression of miR-378, the regulatory mechanism by which ELK3 regulates ovarian cancer remains unclear." (PMID 36243865, 2022). "However, the potential gene regulatory mechanism of ELK3 in human ovarian cancer remains unclear." (PMID 36243865, 2022). "Combined with our results, this suggests that the ability of ELK3 to induce chemoresistance in cancer cells might be conserved in TNBC and ovarian cancer cells." (PMID 37422450, 2023).
bladder cancer (3 papers, 2020 to 2024). "In the context of bladder cancer, LINC01106 has been found to influence ELK3 and HOXD8 at the post-transcriptional level, thereby accelerating the disease’s advancement." (PMID 38255219, 2024). "LINC01116 could regulate ELK3 and HOXD8 to promote bladder cancer cells proliferation, migration, and invasion." (PMID 37424068, 2023).
colon cancer (3 papers, 2019 to 2022). "ELK3, which was down-regulated in cancer tissues, may be correlated with colon cancer and CD4+ T cells." (PMID 32571262, 2020). "Perhaps, in Caco-2 colon cancer cells, other specific microRNAs may be able to regulate ELK3 miRNA expression at the post-transcriptional level." (PMID 31744065, 2019).
pancreatic adenocarcinoma (3 papers, 2021 to 2024). "To dissect the molecular mechanism of ELK3 overexpression in PDAC, we first explored the genetic or epigenetic dysregulation of ELK3 in pancreatic adenocarcinoma (TCGA, Firehose Legacy) from the cBioPortal database." (PMID 34409034, 2021). "Furthermore, a study revealed that UCHL5 promotes cancer stemness and tumor progression in pancreatic adenocarcinoma (PAAD) by stabilizing ELK3, demonstrating its diversity in tumor regulation." (PMID 39068672, 2024).
squamous cell carcinoma (3 papers, 2016 to 2020). A carcinoma arising from squamous epithelial cells. "Malignant progression of squamous cell carcinoma (SCC) requires ELK3 expression, and knockdown (KD) of ELK3 severely impairs tumor growth and inhibits progression from benign papillomas to SCC." (PMID 27556500, 2016). "For example, Ets2 and Elk3 genes in squamous cell carcinoma can upregulate specific SEs." (PMID 31105558, 2019).
breast tumor (2 papers, 2019). "In this study, we demonstrate that LECs produce exosomes that are able to promote breast tumor progression and that ELK3 expressed in LECs promotes the expression of pro-oncogenic miRNAs and suppresses antioncogenic miRNAs, which are transferred to tumor cells via exosomes." (PMID 31182803, 2019). "ELK3 was highly expressed in breast tumor, esophageal tumor, head and neck tumor, and liver tumor." (PMID 31018569, 2019).
cervical cancer (2 papers, 2009 to 2020). A primary or metastatic malignant neoplasm involving the cervix. "Moreover, ELK3 down-regulation was observed in malignant mesothelioma and cervical cancer cells, thus suggesting a potential role as a tumor suppressor." (PMID 19327144, 2009).
hepatocellular carcinoma (2 papers, 2020 to 2021). A malignant tumor that arises from hepatocytes. "A previous study shows that ELK3 is upregulated in hepatocellular carcinoma and enhances the migration and invasion of hepatocellular carcinoma cells." (PMID 34976781, 2021). "have observed that ELK3 was upregulated in hepatocellular carcinoma and promoted the migration and invasion of hepatocellular carcinoma cells." (PMID 34976781, 2021).
alcoholic liver diseases (1 paper, 2023). A disorder caused by damage to the liver parenchyma due to alcohol consumption. "Analyses of human samples and murine models of alcoholic liver disease (ALD) reveal that the Elk-3 target Abhd10 ameliorates hepatotoxic injury and fibrosis in ALD by downregulating PRDX5 S-palmitoylation." (PMID 37400491, 2023).
B-cell acute lymphoblastic leukaemia (1 paper, 2016). "The positive enrichment for genes with promoters containing Pax4 motifs could be related to the observations that the paralogue Pax5 interacts with Elk3, and aberrant Pax5-Elk3 fusion proteins are found in childhood precursor B-cell acute lymphoblastic leukaemia." (PMID 27427904, 2016).
bone tumours (1 paper, 2016). "In the intracardiac injection studies, Elk3 was detected in the bone tumours and after XRP44X treatment the volumes of the tumours decreased." (PMID 27427904, 2016).
epilepsy (1 paper, 2021). A brain disorder characterized by episodes of abnormally increased neuronal discharge resulting in transient episodes of sensory or motor neurological dysfunction, or psychic dysfunction. "It should be noted, however, that the ETS expression profile is also different in epilepsy; ELF1, ELK1, ELK4, ETS1, ETS2, and ETV1 are expressed at higher levels than ELF4, ELK3, and ETV4, and there is also variability in expression among different types of epilepsy." (PMID 33671331, 2021).
esophageal squamous cell carcinoma (1 paper, 2025). Esophageal squamous cell carcinoma (ESCC) is a type of esophageal carcinoma (EC) that can affect any part of the esophagus, but is usually located in the upper or middle third. "To determine if ELK3’s regulation of the invasion and migration abilities in esophageal squamous cell carcinoma cells is linked to RHBDD1, we performed experiments with overexpressed RHBDD1 and downregulated ELK3." (PMID 40787199, 2025). "This suggests that down-regulating the expression level of ELK3 in esophageal squamous cell carcinoma inhibits the epithelial-mesenchymal transition process to a certain extent." (PMID 40787199, 2025).
exudative vitreoretinopathy (1 paper, 2014). Familial exudative vitreoretinopathy (FEVR) is a rare hereditary vitreoretinal disorder characterized by abnormal or incomplete vascularization of the peripheral retina leading to variable clinical manifestations ranging from no effects to minor anomalies, or even retinal detachment with blindness. "Elk3(−/−) phenotypic features partly resemble human ophthalmologic diseases with tortuous vessels, i.e. retinopathy of prematurity (ROP) and familial exudative vitreoretinopathy (FEVR)." (PMID 25203538, 2014).
liposarcoma (1 paper, 2021). A usually painless malignant tumor that arises from adipose tissue. "We further investigated the genomic alterations that may influence tumor infiltration by leukocytes including RB1 loss in undifferentiated pleomorphic sarcomas and ELK3 amplification in dedifferentiated liposarcomas." (PMID 33980253, 2021).
liver fibrosis (1 paper, 2025). "Previous research has shown that EGR1 is involved in liver fibrosis progression downstream of Elk-3 in CCl4-induced mouse liver fibrotic tissues and human liver cirrhotic tissues." (PMID 40393967, 2025).
lung adenocarcinoma (1 paper, 2023). A carcinoma that arises from the lung and is characterized by the presence of malignant glandular epithelial cells. "Because ID4 functions as a tumor suppressor in lung adenocarcinoma, we examined whether ID4 is a downstream target of ELK3 in TNBC." (PMID 38188675, 2023).
neuroblastoma (1 paper, 2024). Neuroblastoma (NB) is the most common solid, extracranial childhood tumor. "The dysregulation of PAX7 can affect neuroblastoma cell behavior, and the retention of Pax7+ precursors due to Elk3 loss suggests that disruptions in these pathways could contribute to neuroblastoma pathology, where progenitor cells fail to differentiate properly." (PMID 39404397, 2024). "On the other hand, neuroblastoma, a cancer originating from neural crest-derived cells in the sympathetic nervous system, is also related to the roles of PAX7 and Elk3." (PMID 39404397, 2024).
renal carcinoma (1 paper, 2024). A carcinoma arising from the epithelium of the renal parenchyma or the renal pelvis. "The results of cell experiments were performed to compare the mRNA levels of ELK3 and ETS1 between human renal cortical proximal tubular epithelial cell line HK-2 and human renal carcinoma cell line A498." (PMID 38287102, 2024). "ELK3 and ETS1 mRNA levels were compared between human renal cortical proximal tubular epithelial cell line HK-2 and human renal carcinoma cell line A489." (PMID 38287102, 2024).
sarcoma (1 paper, 2021). A usually aggressive malignant neoplasm of the soft tissue or bone. "The presence of ELK3 fusion transcripts was confirmed in our in-house HIPO sarcoma dataset and was validated using Sanger sequencing for 5 cases." (PMID 33980253, 2021).